Y_RNA (Y RNA )
Gene: Miscellaneous RNA gene on chromosome 12 (133,238,455 to 133,238,549, forward strand). Ensembl gene ENSG00000238443.
Homologues: Orthologues: chimpanzee Y_RNA (100% identical). Paralogues in human: Y_RNA (87% identical), Y_RNA (86% identical), Y_RNA (85% identical), RNY3 (84% identical), Y_RNA (84% identical), RNY3P14 (83% identical), RNY3P2 (83% identical), Y_RNA (83% identical), RNY3P16 (82% identical), Y_RNA (82% identical), RNY3P1 (81% identical), Y_RNA (81% identical), and 93 more.